CHST12 (carbohydrate sulfotransferase 12)
Description:
Catalyzes the transfer of sulfate to position 4 of the N-acetylgalactosamine (GalNAc) residue of chondroitin and desulfated dermatan sulfate. Chondroitin sulfate constitutes the predominant proteoglycan present in cartilage and is distributed on the surfaces of many cells and extracellular matrices. Activity toward partially desulfated dermatan sulfate is however lower. Does not form 4, 6-di-O-sulfated GalNAc when chondroitin sulfate C is used as an acceptor.
Synonyms: C4ST-2; C4ST2; C4S-2
Tractability: Antibody: UniProt predicts a signal peptide or a membrane-spanning region. PROTAC: ubiquitination databases record sites on it.
Gene: Protein-coding gene on chromosome 7 (2,403,442 to 2,448,484, forward strand). Ensembl gene ENSG00000136213.
Subcellular location: Golgi apparatus membrane
Subcellular location (Human Protein Atlas): Golgi apparatus
Pathways (Reactome):
Metabolism: CS-GAG biosynthesis
Gene Ontology:
Molecular function: chondroitin 4-sulfotransferase activity; 3'-phosphoadenosine 5'-phosphosulfate binding; sulfotransferase activity
Biological process: chondroitin sulfate proteoglycan biosynthetic process; dermatan sulfate proteoglycan biosynthetic process; proteoglycan biosynthetic process; carbohydrate biosynthetic process; glycoprotein biosynthetic process
Cellular component: membrane; Golgi membrane; Golgi apparatus
Genetic constraint (gnomAD): Loss-of-function variants: 23 observed, 29.04 expected, observed/expected ratio (o/e) 0.79, 90% interval 0.57 to 1.12. The upper end of that interval is the gene's LOEUF score, 1.12, which puts it in group 4 of 6, group 1 being the genes least tolerant of losing a copy. Missense variants: 682 observed, 631.21 expected, observed/expected ratio (o/e) 1.08, 90% interval 1.01 to 1.15. Synonymous variants: 322 observed, 286.23 expected, observed/expected ratio (o/e) 1.12, 90% interval 1.03 to 1.23.
Homologues: Orthologues: chimpanzee CHST12 (99% identical), macaque CHST12 (99% identical), mouse Chst12 (84% identical), rat Chst12 (84% identical), guinea pig Chst12 (83% identical), dog CHST12 (73% identical), pig CHST12 (72% identical), tropical clawed frog chst12 (67% identical), zebrafish chst12a (59% identical), zebrafish chst12b.1 (52% identical), zebrafish CHST12 (48% identical), zebrafish chst12b.2 (47% identical), and 4 more. Paralogues in human: CHST11 (31% identical), CHST8 (30% identical), CHST13 (28% identical), CHST9 (27% identical), CHST14 (25% identical), CHST10 (25% identical).
Diseases named in the same sentence as CHST12 in open-access papers:
CHST12 is named in the same sentence as 24 diseases in open-access papers, as found by Europe PMC text mining. Sharing a sentence is not in itself a finding about the gene and the disease. The quoted sentences say what the papers report.
glioblastoma (3 papers, 2021 to 2023). The most malignant astrocytic tumor (WHO grade IV). "Similar result has been found in the glioblastoma (GBM) case where the CHST12 tissue expression was also associated to the WNT signalling." (PMID 37545696, 2023). "CHST12 is a significant member of the CHST family, and a previous study demonstrated that CHST12 may be a novel biomarker for glioblastoma; it regulates cell proliferation and mobility via the WNT/β-catenin pathway." (PMID 36523430, 2022). "Mutations of CHST3 gene cause skeletal dysplasia, chondrodysplasia, and autosomal recessive multiple joint dislocations while increased tissue expression of CHST11, CHST12 and CHST15 is an unfavourable prognostic factor in ovarian cancer, glioblastoma and pancreatic cancer, respectively." (PMID 37545696, 2023).
pancreatic cancer (3 papers, 2021 to 2023). "Expression analysis further revealed that CDK1, DSC2, ERO1A, MET, PYGL, and SLC35A3 were highly expressed in pancreatic cancer while CHST12 was highly expressed in normal pancreatic tissues." (PMID 33912561, 2021). "CDK1, DSC2, ERO1A, MET, PYGL, and SLC35A3 were highly expressed while CHST12 was decreased in pancreatic cancer." (PMID 33912561, 2021). "However, the specific functions and role of CHST12 in the prognosis of pancreatic cancer and the regulation of TME remain a mystery." (PMID 38333724, 2023). "Likewise, in the paired analysis of normal and tumor tissues, CHST12 was highly expressed in pancreatic cancer tissues (N=41; p=0.038)." (PMID 38333724, 2023). "Similarly, CHST12 was found to be a favorable prognostic factor for pancreatic cancer in this study." (PMID 33912561, 2021). "Increased tissue expressions of CHST11, CHST12 and CHST15 were shown to be unfavourable prognostic factors of ovarian cancer, GBM and pancreatic cancer, respectively." (PMID 37545696, 2023). "Seven GRGs: CDK1, DSC2, MET, PYGL, CHST12, ERO1A, and SLC35A3 were selected to construct the prognostic model related to the overall survival rate of patients with pancreatic cancer." (PMID 33912561, 2021). "Hence, the effects of CHST12 expression on the TME and immunotherapy of pancreatic cancer is a key aspect of our study." (PMID 38333724, 2023).
glioma (2 papers, 2018 to 2021). A benign or malignant brain and spinal cord tumor that arises from glial cells (astrocytes, oligodendrocytes, ependymal cells). "In addition, there is no research on B4GALT7, CHST12, G6PC2 and TPBG in glioma." (PMID 33553434, 2021).
metastatic tumors (2 papers, 2013 to 2015). "Moreover, CHST12 showed a 9 fold mean downregulation in the non-metastatic CRCs, in 90 % of cases, whereas in metastatic tumors its decrease was lower, at around 4 fold, and involved only 70 % of cases (p = 0.011 and p = 0.025)." (PMID 26482785, 2015). "Although some variations were detectable only in non metastatic tumors, most were identified in both IDCs although several genes showed more intense changes in metastatic tumors than in non-metastatic, including PRCAN, CSGALNACT2, HS3ST4 and CHST12." (PMID 23327652, 2013).
bladder cancer (1 paper, 2023). "Using the gene set prioritization module, we found that low CHST12 was related to the increase in the clinical efficacy of immunotherapy in melanoma and bladder cancer." (PMID 38333724, 2023). "We found that high CHST12 mRNA expression is related to the increased efficacy of immunotherapy in melanoma and bladder cancer." (PMID 38333724, 2023). "Using the gene set prioritization module, we found that low CHST12 was related to an increase in the clinical efficacy of immunotherapy in melanoma and bladder cancer." (PMID 38333724, 2023).
hepatocellular carcinoma (1 paper, 2023). A malignant tumor that arises from hepatocytes. "CHST12 has shown a similar effect in hepatocellular carcinoma." (PMID 38333724, 2023).
lupus (1 paper, 2021). "Dysregulation of CHST12 is involved in the occurrence of renal damage in patients with lupus." (PMID 34288811, 2021).
multiple sclerosis (1 paper, 2021). A progressive autoimmune disorder affecting the central nervous system resulting in demyelination. "Furthermore, the high expression of CHST12 was positively associated with the progression of brain diseases, such as multiple sclerosis." (PMID 34288811, 2021).
osteoarthritis (1 paper, 2021). A noninflammatory degenerative joint disease occurring chiefly in older persons, characterized by degeneration of the articular cartilage, hypertrophy of bone at the margins and changes in the synovial membrane. "Reduction in the CHST12 expression was reported in adults with osteoarthritis, while inhibition of CHST12 promoted inflammation." (PMID 34288811, 2021).
ovarian tumours (1 paper, 2023). "The study has shown that CHST11, CHST12 and CHST15 messenger ribonucleic acid (mRNA) tissue expressions in the malignant ovarian tumours were increased compared to the expressions in the non-malignant ovarian tumours (N = 95, P < 0.05 for each gene expression)." (PMID 37545696, 2023).
prostate carcinoma (1 paper, 2022). A carcinoma that arises from epithelial cells of the prostate gland. "CHST12, CHST13, and CHST14 can also mediate C4S sulfations under some circumstances, however, these enzymes did not respond to castration in the prostate cancer progression PDX model." (PMID 35963852, 2022).
tumor (9 papers, 2015 to 2025). "In our study, functional enrichment analysis of CHST12-associated DEGs showed that they are significantly enriched in tumor progression and immune-related signaling pathways." (PMID 38333724, 2023). "For the downregulated genes, Id1, Tor4a, Fam83d, Chst12, Fhod1, Sapcd2, and Gas2l3 are known as proliferative and metastatic oncogenes contributing to tumor progression." (PMID 40231790, 2025). "Through transcriptome analysis, we found that CHST12 mRNA was highly expressed in tumors, but CHST12 protein showed lower expression in PAAD tumor tissues than in normal tissues." (PMID 38333724, 2023). "In the TCGA+GTEx datasets, compared with normal tissues (N=171), tumor tissues (N=179, p < 0.001) expressed high levels of CHST12 mRNA." (PMID 38333724, 2023). "A total of 281 variants were associated with tumor necrosis and five of these variants, in SLC22A1, SLC22A8, CHST12 and UGT2B15, were also associated with OS, prioritizing these for future research." (PMID 36536332, 2022). "Nonetheless, decreased expression of the CHST12 gene in tumor cells produces an anti-tumor effect by acting on the immune cells." (PMID 33912561, 2021). "CHST12 protein expression was also analyzed by immunohistochemistry, and the results showed that the staining in the normal colonic mucosa was reduced in tumor tissue." (PMID 26482785, 2015). "A crucial role for glycosylation in modulating tumor immunity has been demonstrated and CHST12-associated DEG pathway analysis suggested that as a member of glycosylation, CHST12 may play a significant role in tumor microenvironment immunity in PAAD tumors." (PMID 38333724, 2023). "In PAAD, elevated CHST12 mRNA expression might regulate immune cell infiltration into the tumor microenvironment (TME) and may predict clinical outcomes." (PMID 38333724, 2023). "Similarly, the expression of CHST12 increased in GBM tissues than in adjacent tissues and had an important diagnostic value in distinguishing tumor tissues from adjacent tissues." (PMID 34288811, 2021). "Combined with the results of the previous discovery of the post-transcriptional modification of CHST12, our study supports the notion that the decreased expression of CHST12 protein in the TME may produce an anti-tumor effect by acting on the recruitment of immune cells to the TME." (PMID 38333724, 2023). "The current evidence suggests that carbohydrate sulfotransferase 12 (CHST12) is a cancer-related enzyme and is a potential biomarker in some tumor subtypes." (PMID 38333724, 2023). "CHST12 was also downregulated in both types of tumor, with transcription levels decreasing about 60% in non-metastatic and 70% metastatic LSCRCs (p < 0.05), in 80 and 90% of the respective samples." (PMID 29940912, 2018).
cancer (3 papers, 2021 to 2023). A tumor composed of atypical neoplastic, often pleomorphic cells that invade other tissues. "The study results revealed that there was significantly higher mRNA expression of CHST11, CHST12, CHST15 and CHST13 compared to non-malignant tumours." (PMID 37545696, 2023). "Using TISIDB analysis, our findings revealed that CHST12 mRNA was remarkably negatively correlated with CD4 and Type2 T-helper (Th2) cells, the infiltration of which was critical for immunotherapy producing anti-cancer immunity." (PMID 38333724, 2023).
CHST12 also shares sentences with these, for which no sentence is quoted: ovarian carcinoma (2 papers); bacterial infections (1); brain diseases (1); chondrodysplasia (1); colorectal cancer (1); diabetes (1); Heat Stroke (1); Kashin-Beck disease (1); melanoma (1); pancreatic adenocarcinoma (1); skeletal dysplasia (1).